GPRASP2 (G protein-coupled receptor associated sorting protein 2)
Description:
May play a role in regulation of a variety of G protein coupled receptors.
Synonyms: GASP2; FLJ37327; DFNX7
Tractability: PROTAC: ubiquitination databases record sites on it.
Gene: Protein-coding gene on chromosome X (102,712,056 to 102,717,733, forward strand). Ensembl gene ENSG00000158301.
Subcellular location (Human Protein Atlas): Cytosol; Nucleoplasm
Gene Ontology:
Molecular function: G protein-coupled receptor binding; protein binding; amyloid-beta binding
Cellular component: cytoplasm; nucleus; cytosol
Homologues: Orthologues: chimpanzee GPRASP2 (99% identical), macaque GPRASP2 (96% identical), rabbit GPRASP2 (84% identical), pig GPRASP2 (84% identical), dog GPRASP2 (83% identical), guinea pig GPRASP2 (77% identical), rat Gprasp2 (76% identical), mouse Gprasp2 (74% identical), zebrafish armc10 (8% identical), tropical clawed frog armc10 (8% identical), Caenorhabditis elegans Y67A10A.7 (6% identical). Paralogues in human: GPRASP1 (58% identical), ARMCX4 (25% identical), GPRASP3 (21% identical), ARMCX5 (19% identical), ARMCX2 (12% identical), ARMCX1 (12% identical), ARMCX3 (11% identical), ARMC10 (9% identical), ARMCX6 (8% identical), ARMC12 (6% identical).
Diseases named in the same sentence as GPRASP2 in open-access papers:
GPRASP2 is named in the same sentence as 18 diseases in open-access papers, as found by Europe PMC text mining. Sharing a sentence is not in itself a finding about the gene and the disease. The quoted sentences say what the papers report.
Alzheimer disease (2 papers, 2012 to 2021). A progressive, neurodegenerative disease characterized by loss of function and death of nerve cells in several areas of the brain leading to loss of cognitive function such as memory and language. "GPRASP2 encodes a protein that was shown to interact with several GPCRs (G protein-coupled receptors), which are relevant for the signal transduction system in Alzheimer’s disease." (PMID 23066814, 2012).
Anxiety (1 paper, 2024). Intense feelings of nervousness, tension, or panic often arise in response to interpersonal stresses. "Female mice, wild-type (WT), Gprasp2+/− (HET) or Gprasp2−/− (KO) mutants and their progeny were used and behavioural paradigms targeting anxiety, memory, maternal care, and other social behaviours were performed." (PMID 38816497, 2024).
autism (1 paper, 2019). Persistent deficits in social interaction and communication and interaction as well as a markedly restricted repertoire of activity and interest as well as repetitive patterns of behavior. "In addition, GPRASP2 mutations have been found in autism and schizophrenia patients and the downregulation of this gene was observed in a large cohort of brain samples from autism patients." (PMID 30926797, 2019).
endophthalmitis (1 paper, 2021). An infectious process affecting the internal structures of the eye. "Genes known to have a role in G-Protein-coupled receptor pathway were found to be negatively regulated in MDR-PA endophthalmitis and included Rgs7 and Gprasp2." (PMID 35046947, 2021).
hearing loss (1 paper, 2025). "This establishes a theoretical foundation for considering GPRASP2 as a potential target for hearing loss caused by HC deficiency." (PMID 39675768, 2025). "In our previous study, the GPRASP2 mutation p.A573N was cosegregated with the clinical phenotype of syndromic hearing loss (SHL) in male patients." (PMID 39675768, 2025).
neurodevelopmental disabilities (1 paper, 2019). "Here, we investigate the physiological role of Gprasp2, a gene linked to neurodevelopmental disabilities and involved in the postendocytic sorting of G-protein-coupled receptors." (PMID 30926797, 2019).
tumor (2 papers, 2016 to 2025). "Although its role in cancer is unclear, GPCR signaling has been widely recognized for its involvement in tumor proliferation and metastasis, suggesting GPRASP2 may participate in oncogenic pathways via m6A-related post-transcriptional regulation." (PMID 40893943, 2025). "In order to investigate whether the growth of tumor spheroids is dependent on ciliary SmoM2-induced Hh pathway activation, we analyzed Smo and Gprasp2 translocation to the PC and Gli1 protein expression as an indicator for Hh pathway activation." (PMID 26931153, 2016).
neurodevelopmental disorder (1 paper, 2019). A behavioral and cognitive disorder with onset during the developmental period that involves impaired or aberrant development of intellectual, motor, or social functions. "GPRASP2 plays a role in trafficking of GPCRs and mutations in this gene have been linked to neurodevelopmental disorders." (PMID 30926797, 2019). "In addition, the behavioural phenotype of the knockout mice is reminiscent of both ASD and ID, which supports the genetic data implicating GPRASP2 in human neurodevelopmental disorders." (PMID 30926797, 2019).
GPRASP2 also shares sentences with these, for which no sentence is quoted: Alport syndrome (1 paper); autism spectrum disorder (1); Autoimmunity (1); cancer (1); deafness (1); external auditory canal atresia (1); memory impairment (1); neurodegenerative disease (1); oculocerebrorenal syndrome of Lowe (1); schizophrenia (1).